KLF1 (KLF transcription factor 1)
Description:
Transcription regulator of erythrocyte development that probably serves as a general switch factor during erythropoiesis. Is a dual regulator of fetal-to-adult globin switching. Binds to the CACCC box in the beta-globin gene promoter and acts as a preferential activator of this gene. Furthermore, it binds to the BCL11A promoter and activates expression of BCL11A, which in turn represses the HBG1 and HBG2 genes. This dual activity ensures that, in most adults, fetal hemoglobin levels are low. Able to activate CD44 and AQP1 promoters. When sumoylated, acts as a transcriptional repressor by promoting interaction with CDH2/MI2beta and also represses megakaryocytic differentiation.
Synonyms: EKLF; CDAN4A; CDAN4B; EKLF/KLF1
Tractability: PROTAC: UniProt records ubiquitination sites on it; ubiquitination databases record sites on it.
Target class: Transcription factor
Gene: Protein-coding gene on chromosome 19 (12,884,422 to 12,887,201, reverse strand). Ensembl gene ENSG00000105610.
Subcellular location: Nucleus
Subcellular location (Human Protein Atlas): Nucleoplasm
Gene Ontology:
Molecular function: protein binding; RNA polymerase II cis-regulatory region sequence-specific DNA binding; transcription cis-regulatory region binding; ubiquitin binding; DNA-binding transcription factor activity; DNA-binding transcription factor activity, RNA polymerase II-specific
Biological process: erythrocyte differentiation; positive regulation of DNA-templated transcription; protein destabilization; regulation of DNA-templated transcription; ubiquitin-dependent protein catabolic process; regulation of transcription by RNA polymerase II; cellular response to endothelin; maternal process involved in female pregnancy
Cellular component: chromatin; nucleoplasm; nucleus
Genetic constraint (gnomAD): Loss-of-function variants: 34 observed, 25.15 expected, observed/expected ratio (o/e) 1.35, 90% interval 1.03 to 1.78. The synonymous counts are far from expectation, so gnomAD's model fits this gene poorly and the ratio says little. Missense variants: 508 observed, 449.24 expected, observed/expected ratio (o/e) 1.13, 90% interval 1.05 to 1.22. Synonymous variants: 262 observed, 201.61 expected, observed/expected ratio (o/e) 1.3, 90% interval 1.17 to 1.44.
Homologues: Orthologues: chimpanzee KLF1 (99% identical), macaque KLF1 (97% identical), dog KLF1 (83% identical), pig KLF1 (80% identical), guinea pig KLF1 (75% identical), mouse Klf1 (71% identical), rat Klf1 (66% identical), Drosophila melanogaster luna (25% identical). Paralogues in human: KLF4 (35% identical), KLF2 (34% identical), KLF5 (27% identical), KLF7 (24% identical), KLF15 (24% identical), KLF6 (23% identical), KLF8 (23% identical), KLF12 (23% identical), KLF3 (22% identical), SP5 (21% identical), KLF10 (21% identical), KLF11 (21% identical), and 10 more.
Diseases named in the same sentence as KLF1 in open-access papers:
KLF1 is named in the same sentence as 78 diseases in open-access papers, as found by Europe PMC text mining. Sharing a sentence is not in itself a finding about the gene and the disease. The quoted sentences say what the papers report.
anemia (26 papers, 2009 to 2025). A reduction in the number of red blood cells, the amount of hemoglobin, and/or the volume of packed red blood cells. "CDA IV arises due to a heterozygous mutation E325K in the second zinc finger of KLF1, and results in severe anemia characterized by an increased prevalence of binucleate erythroid cells in the bone marrow." (PMID 40977284, 2025). "KLF1 variants in humans lead to diverse phenotypes ranging from a benign increase in fetal hemoglobin levels to severe anemia." (PMID 40977284, 2025). "To assess the effectiveness of AAVS1-iABE8e iPSCs in generating mutations in target genes, we designed gRNAs to introduce four mutations associated with human diseases causing severe anemia: KLF1 Y290H and L300P and CDAN1 T884A and F360L." (PMID 38081875, 2023). "CDA IV (OMIM: 613673) is a dominantly inherited anemia caused by a point mutation in the second zinc finger of KLF1 (c.973G > A; p.E325K)." (PMID 31126231, 2019). "Studies on the effect of the KLF1 Nan variant in adult mice have revealed that these animals display life-long anemia." (PMID 30921348, 2019). "Compound heterozygosity for KLF1 mutations is associated with microcytic hypochromic anemia and increased fetal hemoglobin." (PMID 30863397, 2019). "Here we show that an enhanced NFATc1 activity induced by increased integrin-cAMP signaling plays a critical role in the dysregulation of Klf1 expression and thereby cause anemia in Il2-/- mice." (PMID 29515759, 2018). "KLF1 knock-out mice die of severe anemia secondary to β-globin deficiency about 2 weeks after embryonic formation." (PMID 28423541, 2017). "Mutations in KLF1 lead to diverse phenotypes ranging from mild to severe anemias." (PMID 40977284, 2025). "Notably, a variant in the homologous residue in mouse Klf1, Glu339Asp, underlies semi-dominant neonatal anaemia (Nan)." (PMID 36231031, 2022). "These external conditions include (a) α-thalassemia and iron deficiency anemia which may have influence on lowering HbA2 levels and (b) mutations in the Krüppel-like Factor 1 (KLF1) gene which is known to associate with elevation in HbA2 level." (PMID 29295702, 2018). "Bidirectional Effects on Erythropoiesis: While ASXL1 truncations repress erythroid differentiation via GATA1/KLF1 silencing (contributing to anemia), concomitant H3K27me3 loss at proliferative loci (e.g., HOXA9) may paradoxically expand early erythroid progenitors." (PMID 40772034, 2025). "The fact that only 1 patient has been described to date that is null for KLF1 displaying severe anemia and complete transfusion dependency indicates the importance of KLF1 in erythropoiesis." (PMID 34535703, 2021). "On the other hand, abnormal macrophage differentiation in EMP-null and KLF1-null mice reportedly led to significantly impaired erythropoiesis and anemia." (PMID 33644032, 2020). "As for GATA1, the first evidence for an essential role in erythropoiesis came from the observation that KLF1 knockout mice die in utero around E15 due to fatal anemia." (PMID 30809156, 2019). "Klf1−/− mice die in utero from severe anemia and KLF1 null humans display severe hydrops fetalis, which is lethal without intervention." (PMID 31126231, 2019). "A comparison of DEGs in β‐thalassemia versus SCD and KLF1‐null anemia shows that while many DEGs involved in response to hemolysis, iron homeostasis, and anemia were common to these disorders, over 200 DEGs were unique to β‐thalassemia." (PMID 31134759, 2019). "Krüppel-like factor 1 (KLF1) is an essential transcription factor for erythroid development, as demonstrated by Klf1 knockout mice which die around E14 due to severe anemia." (PMID 30921348, 2019). "Furthermore, the electrophoretic parameter HbA2-dependent screening may also give rise to false negative or false positive results based on the coinheritance of the α-globin and Krüppel-like Factor 1 (KLF1) genes mutations, the gamma-globin gene promoter mutations, and iron deficiency anemia." (PMID 29295702, 2018).
anemia (continued). "Here, we compared adult Nan and WT-PHB sorted spleen erythroid precursors as a way to discern effects on gene expression specific to Nan-KLF1 induced anemia." (PMID 30143664, 2018). "Though, the reasons behind this are not completely known, we have reported that Klf1 suppression is a major factor for anemia development in Il2−/− mice." (PMID 29515759, 2018). "We have shown recently that Il2-/- mice develop severe anemia due to defects in KLF1 activity during BM erythropoiesis." (PMID 29515759, 2018). "The critical role of these TFs in defining erythroid cell state is highlighted by human genetic studies that have identified causal mutations for various forms of anemia in GATA1 and KLF1." (PMID 25521328, 2014). "KLF1 is essential for definitive murine erythropoiesis, KLF1-null mice dying of anemia at E15.5 of gestation." (PMID 23056320, 2012). "Mice lacking Klf1 die at approximately embryonic day 15 (E15) due to severe anaemia, attributed to the loss of β-globin expression in the first instance, suggesting a β-thalassaemic phenotype." (PMID 36231031, 2022). "Importantly, Klf1 KO mice were found to die in utero due to severe anemia, whereas residual circulating RBCs retained their nuclei." (PMID 33644032, 2020). "Here, we performed RNAseq using flow cytometric-sorted spleen erythroid precursors from adult Nan and WT littermates rendered anemic by phlebotomy to identify global transcriptome changes specific to the Nan Klf1 mutation as opposed to anemia generally." (PMID 30143664, 2018). "Most cases carrying monoallelic KLF1 mutations do not display anemia." (PMID 34249106, 2021). "Because whole-blood cell analysis and Hb electrophoresis are required items for anemia diagnosis and thalassemia screening, the key RBC parameters and the constitution of Hb were compared in patients with TI or KLF1-AM." (PMID 34249106, 2021). "Hence, it comes as no surprise that Klf1 knockout embryos die due to severe anemia, and that the phenotype is not rescued by exogenous expression of a β-like globin gene." (PMID 30921348, 2019). "Several transcription factors regulating haematopoiesis, Tal1, Gata1, Zfpm1 and Klf1 were expressed at consistently lower levels in C57BL/6 mice suggesting that these mice have a lower haematopoietic capacity and therefore less ability to recover from haemolysis induced anaemia after infection." (PMID 19365556, 2009).
thalassemia (13 papers, 2016 to 2025). An inherited blood disorder characterized by a decreased synthesis of one of the polypeptide chains that form hemoglobin. "Because KLF1 mutations are found significantly more frequently in thalassemia endemic regions such as southern China, it is important for physicians in these regions to distinguish between HHA caused by β-thalassemia from HHA caused by KLF1 mutations." (PMID 34249106, 2021). "For example, Hb A2 is lowered by both iron deficiency and α-thalassaemia, but is elevated by mutations in the Krüppel-like Factor 1 (KLF1) gene." (PMID 27756326, 2016). "Further understanding of the multiple functions of KLF1 in erythropoiesis is achieved by this study, which also emphasizes the possibility that a subset of KLF1 mutations may be responsible for the severity of the thalassemia phenotype." (PMID 37106711, 2023). "Therefore, based on these results, our study adds new light to the significance of KLF1 mutations by showing that certain KLF1 variants may be causative of worsening effects on the thalassemia phenotype." (PMID 37106711, 2023). "Disruption of the LRF repressor BS or (more potently) the creation of a KLF1 activator BS reactivated HbF and rescued the β-thalassemic phenotype in erythroid cells differentiated from HSPCs collected from patients with β0/β+ thalassemia." (PMID 36333351, 2022). "The effect of rs2228104 is reminiscent of primary modifier genes in thalassemia; indeed, KLF1 (Kruppel-like factor 1) variants are overrepresented among patients with thalassemia intermedia compared to thalassemia major." (PMID 33666875, 2021). "The variability in severity of thalassemias, especially β-thalassemia, involves many gene loci, some of which are directly involved with defects in α, β, or γ globin synthesis, whereas others, related to other genes such as KLF1, BCL11A." (PMID 32671092, 2020). "Our study confirmed the ameliorative effect on the thalassemia phenotype for some of these variants but also raised the notion that certain mutations may have deteriorating effects by increasing KLF1 expression levels or enhancing its transcriptional activity." (PMID 37106711, 2023). "In another Chinese cohort, the prevalence of KLF1 mutations was found to be significantly higher (1.25% vs. 0.08%) in patients from the endemic thalassemia region in south China (n = 3839) than in patients in the non-thalassemia endemic region in north China (n = 1190)." (PMID 34070036, 2021). "However, there were no KLF1 mutations in a matched control group of 110 samples referred for thalassemia screening but with normal HbF levels (<1.0%)." (PMID 34070036, 2021). "Recently, a designed targeted gene panel, which included all eight globin genes and validated modulators (KLF1, BCL11A, and MYB), was applied in molecular screening and clinical genotyping in thalassemia." (PMID 30809867, 2019). "Lentiviral-mediated KLF1 knockdown of normal (n = 3) and HbE/β0-thalassemia (n = 3) erythroblasts revealed that the expression of the γ–globin gene suppressor BCL11A decreased due to the absence of KLF1, which in turn activates the γ–globin gene and elevates HbF levels." (PMID 34070036, 2021).
leukemia (8 papers, 2011 to 2021). A malignant (clonal) hematologic disorder, involving hematopoietic stem cells and characterized by the presence of primitive or atypical myeloid or lymphoid cells in the bone marrow and the blood. "To begin our evaluation of human KLF1 genomic status, we focused first on sequencing human leukemia cell lines that retain erythroid and/or megakaryocytic features." (PMID 29700354, 2018). "We queried whether its mutation might play a role in red cell malignancies by genomic sequencing of the KLF1 transcription unit in cell lines, erythroid neoplasms, dysplastic disorders, and leukemia." (PMID 29700354, 2018). "To assess whether the KLF1‐ERT2 fusion protein could activate the expression of KLF1 target genes within a hematopoietic context, we used the K562 human leukemia cell line that could be induced to differentiate into the erythroid cells." (PMID 28026072, 2017). "To investigate the significance of Class I HDACs (HDAC1, HDAC2, HDAC3, and HDAC8), HDAC11, and Klfs (Klf1, KLf3, Klf4, and Klf7) in the pathogenesis of human leukemia, we used real-time RT-PCR to evaluate the expression of HDACs and Klfs in bone marrow samples from human leukemia patients." (PMID 25341045, 2014). "As a consequence, GATA2 alone is not sufficient to inhibit CBFβ-MYH11-caused leukemia, and it maybe has greater functional relevance only in context with overexpression of other regulators like KLF1." (PMID 30850577, 2019).
congenital dyserythropoietic anemia (7 papers, 2018 to 2025). Congenital dyserythropoietic anemia (CDA) is a heterogenous group of hematological disorders of late erythropoiesis and red cell abnormalities that lead to anemia. "Congenital Dyserythropoietic Anemia (CDA) type IV (OMIM: 613673) is a severe autosomal dominant disease due to a missense mutation in the DNA-binding domain of human KLF1 (E325K)." (PMID 31126231, 2019). "It has been recognized that a special case of a genetic variant of KLF1 is causative of congenital dyserythropoietic anemia (CDA) variant (type IV) in addition to the accompanying HPFH already reported." (PMID 33066815, 2020). "This work provides insight into the dominant molecular mechanism of Congenital Dyserythropoietic Anemia Type IV (CDA IV) which is caused by a point mutation (E325K) in the DNA-binding domain of KLF1." (PMID 31126231, 2019). "Haploinsufficiency in KLF1 causes hereditary persistence of fetal hemoglobin (HPFH), and a specific mutation in the DNA-binding domain of KLF1 causes type IV congenital dyserythropoietic anemia (CDA)." (PMID 30087616, 2018). "One such pathogenic variant that we and others have characterized is a heterozygous missense change in the zinc finger domain of KLF1 (p.E325K) that leads to congenital dyserythropoietic anemia (CDA) type IV." (PMID 40977284, 2025). "Mutations in the KLF1 gene have been reported to interfere with the erythropoiesis process, thus leading to severe hematological disorders, including congenital dyserythropoietic anemia (CDA) and congenital hemolytic anemia." (PMID 37106711, 2023).
dyserythropoietic anemia (6 papers, 2018 to 2024). "Furthermore, among the 18 KLF proteins, only KLF1, KLF6, and KLF11 have MIM phenotype numbers, associating them with dyserythropoietic anemia (613673), prostate (176807) and gastric (613659) cancers, and maturity-onset diabetes of the young, type VII (610508), respectively." (PMID 39202416, 2024). "Other very rare types of CDA are caused by autosomal dominant mutations in KIF23 (Kinesin Family Member 23, CDA type III), KLF1 (Kruppel-Like Factor 1, CDA type IV) or X-linked mutations in GATA1 (GATA Binding Protein 1, X-linked thrombocytopenia with or without dyserythropoietic anemia)." (PMID 33672223, 2021).
hemoglobinopathy (5 papers, 2018 to 2023). "Accordingly, several reports have revealed that heterozygosity for loss-of-function mutations in KLF1 can ameliorate the severity of hemoglobinopathies by leading to persistent fetal globin gene expression in adult life (HPFH)." (PMID 37106711, 2023). "In another cohort of patients with hemoglobinopathies (n = 131) and elevated HbF levels, 11 different mutations in the KLF1 gene were observed." (PMID 34070036, 2021). "During the era of next‐generation sequencing, the bulk of variants and polymorphisms have been identified in the hemoglobinopathy‐relevant genes, especially in modifier genes, such as the KLF1, BCL11A, and HMIP regions." (PMID 31286593, 2019).
melanoma (4 papers, 2018 to 2024). A malignant, usually aggressive tumor composed of atypical, neoplastic melanocytes. "The Klf1(K74R) mutation also protected the mice from metastasis of melanoma cells and reduced melanoma growth in the subcutaneous cancer cell inoculation assay." (PMID 38752723, 2024). "It appeared that male as well as female Klf1(K74R) mice in the B6 genetic background had significantly fewer pulmonary melanoma foci than the corresponding WT mice." (PMID 38752723, 2024). "Anti-cancer capability of Klf1(K74R) mice as analyzed by the experimental melanoma metastasis assay." (PMID 38752723, 2024). "Our experiments indicated that Klf1(K74R) bone marrow carried the anti-metastasis capability that prevented melanoma cell colonization in the lungs of recipient mice." (PMID 38752723, 2024). "First, both young (2-month-old) and aged (24-month-old) Klf1(K74R) mice had higher anti-metastasis ability against the injected melanoma cells than WT mice of age-dependent groups." (PMID 38752723, 2024). "In particular, we show that BMMNC from Klf1(K74R) mice could confer 2-month-old WT recipient mice with the anti-cancer capability against melanoma." (PMID 38752723, 2024). "Furthermore, we show that the Klf1(K74R) mice are resistant to carcinogenesis of not only melanoma, but also other cancers such as hepatocellular carcinoma." (PMID 38752723, 2024). "Significantly, the anti-cancer capability, in particular that against melanoma as well as hepatocellular carcinoma, and lifespan-extending property of Klf1(K74R) mice, could be transferred to wild-type mice via transplantation of their bone marrow mononuclear cells at a young age of the latter." (PMID 38752723, 2024). "Similar to our data from melanoma cell lines, we observed some VEGF targets in the top 65 DEGs, such as CHI3L1, KLF1 and ESM1." (PMID 30242167, 2018). "The anti-cancer capability of Klf1(K74R) mice was not restricted to melanoma." (PMID 38752723, 2024).
sickle cell disease (4 papers, 2016 to 2024). Sickle cell anemias are chronic hemolytic diseases that may induce three types of acute accidents: severe anemia, severe bacterial infections, and ischemic vasoocclusive accidents (VOA) caused by sickle-shaped red blood cells obstructing small blood vessels and capillaries. "We compare our findings with published results of RNA‐sequencing analysis of sickle cell disease and erythroblasts from a KLF1‐null neonate with hydrops fetalis, and recognize similarities and differences in their transcriptional expression patterns." (PMID 31134759, 2019). "We compare our findings with published results of RNA‐sequencing analysis of sickle cell disease (SCD) and erythroblasts from a KLF1‐null neonate with hydrops fetalis, and recognize similarities and differences in their transcriptional expression patterns." (PMID 31134759, 2019).